TRPM2 (transient receptor potential cation channel subfamily M member 2)
Diseases named in the same sentence as TRPM2 in open-access papers (continued):
Sharing a sentence is not in itself a finding about the gene and the disease.
melanoma (19 papers, 2015 to 2025). A malignant, usually aggressive tumor composed of atypical, neoplastic melanocytes. "The data thus suggested that antagonism of TRPM2 is a potential strategy to efficaciously treat melanoma patients that harbor the well-known B-raf or N-ras mutations or contain melanoma neoplasms that are drug-resistant via drug efflux pumps." (PMID 37445615, 2023). "Reduced levels of TRPM2-TE via stable antisense downregulation caused increased susceptibility to cell death in melanoma cells." (PMID 37445615, 2023). "The two splice variant transcripts identified via computational studies, TRPM2-TE and TRPM2-AS, were shown to be overexpressed in melanoma." (PMID 37445615, 2023). "Another study revealed that overexpression of TRPM2 increased melanoma susceptibility to apoptosis and necrosis." (PMID 30881453, 2019). "This splice variant is upregulated in melanoma, and either prevention of its synthesis or exogenous overexpression of full-length TRPM2 renders melanoma cells more susceptible to apoptosis and necrosis." (PMID 27983625, 2016). "Previous study has shown that transient receptor potential melastatin (TRPM) is expressed on melanoma cells, and the member TRPM2 is conferring susceptibility to cell death upon oxidative stress." (PMID 26336993, 2015). "Interestingly, the knockout of TRPM2-TE enhances the susceptibility of melanoma cells to apoptosis and necrosis, suggesting a potential role of this variant in tumor survival mechanisms." (PMID 39633507, 2024). "In melanoma, two splice variant transcripts, TRPM2-TE and TRPM2-AS, are notably upregulated." (PMID 39633507, 2024). "The mutation of TRPM2 most commonly occurred in melanoma, with mutation frequency up to almost 15%." (PMID 37569287, 2023). "Moreover, functional activation of TRPM2 has been associated with highly metastatic melanoma cells." (PMID 36614330, 2023). "Thus, it appears that TRPM2 and its splice variants have novel roles in melanoma cells." (PMID 37445615, 2023). "This review highlights the physiological expression of key TRP subfamilies (TRPM1, TRPM7, TRPM8, TRPV1, TRPV4, and TRPM2) in melanocytes and discusses their dysregulation in melanoma cells." (PMID 40869148, 2025). "TRPM2, which is responsive to oxidative stress, supports melanoma cell survival under metabolic stress." (PMID 40869148, 2025). "Together, these findings underscore the complex yet targetable roles of oncogenic and stress-adaptive TRP isoforms in melanoma, including TRPM2." (PMID 40869148, 2025). "The inhibition or genetic silencing of TRPM2 has been shown to sensitize melanoma cells to oxidative stress and reduce their capacity to withstand cytotoxic insults, thereby enhancing the efficacy of chemotherapeutic agents." (PMID 40869148, 2025). "We will subsequently provide evidence that one strategy in melanoma to overcome drug resistance, which either arises through the presence of drug efflux pumps or the evasion of apoptotic processes, is to target TRPM2." (PMID 37445615, 2023). "In this regard, Ferrera and co-authors demonstrated that Chl-T activated TRPM2 channel in a melanoma cell line (IGR39), thus inducing a dramatic increase in intracellular Ca2+ content." (PMID 36614330, 2023). "Our study therefore demonstrates the potential significance of TRPM2 antagonism being used as a viable strategy to treat a wide variety of melanoma patients in the future." (PMID 37445615, 2023). "One unique member, TRPM2, appears to have notable therapeutic potential in the treatment of melanoma." (PMID 37445615, 2023). "The targeting of TRPM2 therefore has the potential to provide additional treatment options for melanoma patients in the future." (PMID 37445615, 2023). "The potential of TRPM2 in melanoma treatment is based on the emerging essential role that this cation channel accomplishes in melanoma cells." (PMID 37445615, 2023).
melanoma (continued). "Previous and recent studies have demonstrated increased TRPM2 expression levels in melanoma, as well as important roles for TRPM2 in melanoma growth, proliferation, and survival." (PMID 37445615, 2023). "In order to establish TRPM2 as a rational therapeutic target in melanoma, it is critical that future studies resolve these questions." (PMID 37445615, 2023). "In human melanoma cell lines that contain drug resistance genes and those that exhibited all genotypes, antagonism of TRPM2 led to significant dose-dependent decreases in growth and proliferation, as well as dose-dependent increases in cell death." (PMID 37445615, 2023). "A recent study demonstrated increased expression of TRPM2 transcripts in a primary human melanoma cell line and a human metastatic melanoma cell line." (PMID 37445615, 2023). "TRPM2 inhibition using clotrimazole or knockdown via RNAi led to decreased growth and proliferation, and increased cell death in all melanoma lines investigated." (PMID 37445615, 2023). "In cell culture, higher expression of TRPM2 induced melanoma cell proliferation, migratory ability, and invasiveness." (PMID 36614330, 2023). "We will subsequently provide evidence that one strategy for successfully treating mutant melanoma is to target TRPM2." (PMID 37445615, 2023). "Antagonism of TRPM2 channel leads to antitumor effects in human melanoma cells, including those that are potentially unresponsive to current treatments due to the expression of drug resistance genes." (PMID 36081847, 2022). "Ferrera and coworkers reported that potassium ion channels of BK and KCa3.1 were overexpressed in human melanoma cells, and activation of these ion channels were mediated by calcium influx through TRPM2 oxidation." (PMID 35456964, 2022). "TRPM2 represents a potentially novel, efficacious and readily accessible treatment option for patients with melanoma." (PMID 36081847, 2022). "On the other hand, several metastatic lines—including IGR37—regained significant expression of TRPM1 and showed reduced expression of KCNMA1, KCNN4, and TRPM2, compared to the primary melanoma lines (third row)." (PMID 34445066, 2021). "Two TRPM2 mRNA transcripts, one antisense transcript and one truncated TRPM2 transcript, were shown to be increased in 80% of metastatic melanoma cell lines." (PMID 25760245, 2015). "Functional analysis of the protein products of these transcripts demonstrated that overexpression of wild-type TRPM2 or knockout of the truncated TRPM2 transcript increased cytotoxicity in melanoma cells." (PMID 25760245, 2015). "We found that the sustained Ca2+ signaling, mediated by ADPR and TRPM2, was correlated with polarized degranulation and cytolytic activity of NK cells against the melanoma tumor cell line B16F10." (PMID 25879940, 2015). "Inhibiting TRPM2 has been shown to sensitize melanoma cells to redox imbalance and enhance responses to chemotherapeutic agents, positioning it as a potential metabolic checkpoint in melanoma therapy." (PMID 40869148, 2025). "This suggests that TRPM2 may serve as a metabolic and stress-response modulator in melanoma, and its blockade could represent a viable strategy to exploit the tumor’s vulnerability to redox imbalance." (PMID 40869148, 2025). "Among these, TRPM2 also warrants attention due to its emerging role in melanoma biology." (PMID 40869148, 2025). "Another TRP channel that plays a distinctive role in melanoma progression is TRPM2." (PMID 40869148, 2025). "Under the treatment of Chl-T, TRPM2 on the cell membrane of melanoma can also increase the activation of two other potassium channels (BK channel and KCa3.1) on the stimulating membrane by mediating intracellular Ca2+, which are involved in the progression of melanoma." (PMID 39633507, 2024). "However, recent studies regarding TRPM2 in melanoma within the last several years have provided significant insight into its possible roles and importance in this condition." (PMID 37445615, 2023).
melanoma (continued). "In particular, recent studies have demonstrated the emerging importance of TRPM2 in melanoma." (PMID 37445615, 2023). "The studies appear to support the view that TRPM2 is a promising therapeutic target in melanoma." (PMID 37445615, 2023). "TRPM2 is thus an emerging target in the treatment of melanoma, where TRPM2 antagonism may offer an additional treatment option for melanoma patients in the future." (PMID 37445615, 2023). "Along with antitumor effects, TRPM2 targeting may prove to offer additional benefits, such as the prevention of melanoma." (PMID 37445615, 2023). "TRPM2 was capable of inducing melanoma apoptosis and necrosis." (PMID 30881453, 2019). "Thus, pharmacological targeting of TRPM2 might represent a novel therapeutic approach to reduce the metastatic potential of melanoma cells and could complement classical radiation therapy or chemotherapy." (PMID 36614330, 2023). "Taken together, the results demonstrated important roles for TRPM2, TRPM1, and potassium gating in the progression of melanoma." (PMID 37445615, 2023). "TRPM2, TRPM8, TRPV1, and TRPV2 have been identified in melanoma cell lines, where their expression and function confer susceptibility to apoptosis and necrosis." (PMID 34831352, 2021). "We noticed robust Ca2+ signals in both TRPM2+/+ and TRPM2−/− NK cells upon contact with B16F10 cells, a melanoma tumor cell line." (PMID 25879940, 2015). "However, because of their emerging roles in melanoma, where they are hypothesized to be significant regulators in the process or cascade of events important for melanoma cell progression or survival, this review will primarily introduce TRPMs 1, 7, and 8, and focus on TRPM2." (PMID 37445615, 2023).
Sepsis (14 papers, 2015 to 2024). Sepsis is defined as life-threatening organ dysfunction caused by a dysregulated host response to infection. "The absence of TRPM2 channels improved neuroethology and pathological changes and decreased inflammatory cytokines and apoptosis proteins in TRPM2 knock-out mice in the LPS-induced sepsis model associated with encephalopathy infection." (PMID 39329114, 2024). "In contrast, there is evidence to suggest that IL-6 release was increased in TRPM2-deficient mice in sepsis model." (PMID 32513195, 2020). "In a murine sepsis model induced by intraperitoneal injection of Escherichia coli, TRPM2-/- mice exhibited a significantly increase in mortality rate and bacterial burden compared with WT mice, thereby exacerbating inflammatory responses." (PMID 39007141, 2024). "Similar enhanced inflammatory activity has also been observed in TRPM2 KO mice in response to other infection models, including lung infection triggered by P. aeruginosa, sepsis triggered by E. coli, or polymicrobial sepsis." (PMID 37576339, 2023). "Another study by revealed that intraperitoneal injection of 10 mg/kg quercetin protected murine sepsis by inducing macrophage M2 polarization via the TRPM2 dependent calcium influx and AMPK/ATF3 activation." (PMID 36588685, 2022). "For example, during experimental sepsis in mice infected with Listeria monocytogenes, the TRPM2 cation channel modulated membrane depolarization, Ca2+ mobilization, and subsequent ROS generation." (PMID 33567720, 2021). "Taken together, these results support the notion that TRPM2-mediated Ca2+ influx is important in up-regulating the HO-1 expression and enhancing bacterial clearance during sepsis." (PMID 26300888, 2015). "A recent study has examined the role of TRPM2 channels in regulating HO-1 expression in sepsis using cecal ligation and puncture (CLP)-induced model." (PMID 26300888, 2015). "Furthermore, TRPM2−/− mice have been reported to experience increased mortality, suggesting the potential for targeting TRPM2 channel as an immunoadjuvant therapy for sepsis in humans." (PMID 38731999, 2024). "TRPM2 may be an interesting future drug target, for instance in controlling excess neutrophil invasion in conditions such as sepsis." (PMID 33927223, 2021). "Additionally, it has been suggested that TRPV4 and TRPM2 antagonists may have therapeutic potential in treating sepsis." (PMID 38731999, 2024). "In a murine model of sepsis induced by cecal ligation and puncture (CLP), compared with WT mice, TRPM2 KO mice exhibited a significantly increase in mortality rate." (PMID 39007141, 2024). "Considering the pro-inflammatory effects of TRPM2 in IBD, this channel could also be a potential target for sepsis therapy." (PMID 38731999, 2024). "Additionally, TRPM2 and TRPM4 channels have been shown to enhance bacterial clearance and regulate inflammatory responses in CLP-induced sepsis." (PMID 38731999, 2024). "In this study, a lack of TRPM2 resulted in reduced sepsis survival, and in neutrophils led to enhanced depolarization, dysregulation of intracellular Ca2+, and aggravated oxidative burst, all of which might be harmful to the host." (PMID 33567720, 2021).
bipolar disorder (13 papers, 2016 to 2024). A disorder of the brain that causes unusual shifts in mood, energy, activity levels and the ability to carry out day-to-day tasks. "Studies using TRPM2-deficient mice have shown behaviors related to bipolar disorder 50, possibly explaining the increased somatic burden seen in individuals with cold hypersensitivity." (PMID 38253633, 2024). "The genetic etiology of TRPM2 has also been associated with increased susceptibility to bipolar disorder (BD)." (PMID 37576339, 2023). "Fine mapping linkage analysis showed that TRPM2 on chromosome 21q is associated with bipolar disorder." (PMID 36902145, 2023). "Fine mapping linkage analysis identified that TRPM2 on chromosome 21q is associated with bipolar disorder." (PMID 33644051, 2021). "While it is known that TRPM2 activation leads to Ca2+ entry to cells and is linked to diseases like ischemia-reperfusion injury and bipolar disorder, the physiological function of TRPM2 is controversial." (PMID 31662029, 2019). "Likewise, loss-of-function mutations in another Ca2+-channel – Transient receptor potential cation channel, subfamily M, member 2 (TRPM2) – are also associated with human bipolar disorder and Trpm2 null mice display manic-like behaviours." (PMID 37730845, 2023). "Notably, the D543E mutation induces loss of function of TRPM2 activities, and Trpm2 KO mice exhibit bipolar disorder-related behaviors, such as mood disturbances and impairments in social cognition." (PMID 33644051, 2021). "Furthermore, a SNP of TRPM2 has recently been identified as a risk factor for bipolar disorder in a Japanese population." (PMID 33644051, 2021). "It remains unclear whether the variants causing the amino acid mutation of TRPM2 found in bipolar disorder patients are also risk factors in ASD." (PMID 32046066, 2020). "Although TRPM2 variants with a single amino substitution (e.g., Asp543Glu) have been detected in patients with bipolar disorder, the role of these variants in the pathogenesis of the bipolar disorder remains unknown." (PMID 30037128, 2018). "On the other hand, reduced activity of TRPM2 might be linked to amyotrophic lateral sclerosis and Parkinson’s disease dementia, as well as bipolar disorder." (PMID 27383051, 2016). "One of the identified single nucleotide polymorphisms (SNPs) leads to a deletion of TRPM2, and subsequent studies demonstrated that TRPM2 KO mice exhibit bipolar-disorder-related behaviors." (PMID 36902145, 2023). "Mechanistically, the authors provided evidence that loss of TRPM2 induces the inhibitory phosphorylation of GSK-3 via calcineurin, a known kinases in bipolar disorder, and suggest that loss of TRPM2 has a deleterious effects on BD." (PMID 37576339, 2023). "These lines of evidence suggest a link between defects in TRPM2 activities and the pathology of bipolar disorder." (PMID 33644051, 2021). "Studies have found that patients with Type I bipolar disorder exhibit elevated baseline intracellular Ca2+ levels, and a susceptibility locus on chromosome 21q22.3, which includes the TRPM2 gene region, has been identified, suggesting a potential link between TRPM2 and bipolar disorder." (PMID 39007141, 2024). "In addition to the connection between TRPM2 and bipolar disorder, accumulating evidence has indicated the impact of TRPM2 on major depressive disorder." (PMID 33644051, 2021). "The risk of single nucleotide polymorphisms (SNPs) and variants of TRPM2 have been reported in bipolar disorder, but not in ASD." (PMID 32046066, 2020). "Although the significance of GSK-3 in the pathology of bipolar disorder is still debated, these observations suggest that dysregulation of GSK-3 could, at least in part, account for the bipolar disorder-related behaviors induced by hypoactive TRPM2 mutations." (PMID 33644051, 2021). "Interestingly, abnormal functions of TRPM2 have been reported to be risk factors in bipolar disorder, although there are no genetic studies on TRPM2 for ASD." (PMID 32046066, 2020).
bipolar disorder (continued). "Several genes were validated in APA sperm that were associated with autism spectrum disorder (CACNA1H, CNTNAP2, GRIN1, SHANK2, SHANK3, ZNF804A), schizophrenia (TCF3, ZNF804A), and bipolar disorder (COMT, DRD4, GRIN1, MBP, PRKCZ, SHANK2, TRPM2, ZNF804A), and in APA blastocysts (CACNA1H)." (PMID 32610362, 2020). "Therefore, it is possible that TRPM2 mutants and TRPM2 expression during neuronal development may contribute in the pathogenesis of ASD and bipolar disorder." (PMID 32046066, 2020).